RNU6-693P (RNA, U6 small nuclear 693, pseudogene)
Gene: Small nuclear RNA gene on chromosome 1 (172,613,428 to 172,613,534, reverse strand). Ensembl gene ENSG00000251943.
Homologues: Orthologues: chimpanzee U6 (100% identical), dog U6 (79% identical), mouse Gm23124 (56% identical), rat LOC120099422 (52% identical). Paralogues in human: RNU6-214P (76% identical), RNU6-1031P (75% identical), RNU6-1081P (75% identical), RNU6-1289P (75% identical), RNU6-166P (75% identical), RNU6-188P (75% identical), RNU6-1145P (74% identical), RNU6-1316P (74% identical), RNU6-140P (74% identical), RNU6-15P (74% identical), RNU6-19P (74% identical), RNU6-21P (74% identical), and 1285 more.